RMND5A (required for meiotic nuclear division 5 homolog A)
Description:
Core component of the CTLH E3 ubiquitin-protein ligase complex that selectively accepts ubiquitin from UBE2H and mediates ubiquitination and subsequent proteasomal degradation of the transcription factor HBP1. MAEA and RMND5A are both required for catalytic activity of the CTLH E3 ubiquitin-protein ligase complex. Catalytic activity of the complex is required for normal cell proliferation. The CTLH E3 ubiquitin-protein ligase complex is not required for the degradation of enzymes involved in gluconeogenesis, such as FBP1.
Synonyms: FLJ13910; RMD5; GID2; GID2A; p44CTLH; CTLH
Tractability: PROTAC: ubiquitination databases record sites on it; its protein half-life has been measured.
Gene: Protein-coding gene on chromosome 2 (86,720,291 to 86,778,041, forward strand). Ensembl gene ENSG00000153561.
Subcellular location: Nucleus, nucleoplasm; Cytoplasm
Subcellular location (Human Protein Atlas): Nucleoplasm
Pathways (Reactome):
Metabolism: Regulation of pyruvate metabolism
Gene Ontology:
Molecular function: protein binding; ubiquitin protein ligase activity; ubiquitin-protein transferase activity
Biological process: proteasome-mediated ubiquitin-dependent protein catabolic process; protein polyubiquitination
Cellular component: cytoplasm; nucleoplasm; nucleus; ubiquitin ligase complex; cytosol; GID complex
Genetic constraint (gnomAD): Loss-of-function variants: 13 observed, 33.72 expected, observed/expected ratio (o/e) 0.39, 90% interval 0.25 to 0.61. The upper end of that interval is the gene's LOEUF score, 0.61, which puts it in group 2 of 6, group 1 being the genes least tolerant of losing a copy. Missense variants: 196 observed, 353.36 expected, observed/expected ratio (o/e) 0.55, 90% interval 0.49 to 0.62. Synonymous variants: 127 observed, 127.03 expected, observed/expected ratio (o/e) 1, 90% interval 0.87 to 1.16.
Homologues: Orthologues: chimpanzee RMND5A (100% identical), dog RMND5A (100% identical), guinea pig RMND5A (100% identical), macaque RMND5A (100% identical), mouse Rmnd5a (100% identical), rabbit RMND5A (100% identical), rat Rmnd5a (100% identical), pig RMND5A (98% identical), tropical clawed frog rmnd5a (94% identical), Drosophila melanogaster Sou (45% identical), Caenorhabditis elegans gid-2 (28% identical). Paralogues in human: RMND5B (70% identical), MAEA (24% identical).
Diseases named in the same sentence as RMND5A in open-access papers:
RMND5A is named in the same sentence as 34 diseases in open-access papers, as found by Europe PMC text mining. Sharing a sentence is not in itself a finding about the gene and the disease. The quoted sentences say what the papers report.
breast carcinoma (4 papers, 2016 to 2025). "For example, miR-21-mediated regulation of RMND5A expression might be associated with survival in patients with breast cancer." (PMID 38627780, 2024). "RMND5A has also been shown to be a novel potential prognostic marker in breast cancer with higher transcript levels correlating to worse prognosis." (PMID 31885576, 2019). "One of the first interactions that emerged in breast cancer tissue compared to normal tissue was the interaction between RMND5A, EIF5B, SUN2, KLHL18, KDSR, RPSK6KA3 ceRNAs and the miR-338-5p, miR-223-3p, miR-129-5p, miR-642a-5p, miR-3619-5p, and miR-382-5p miRNAs." (PMID 38627780, 2024).
ciliopathy (1 paper, 2022). A genetic disorder of the cellular cilia or the cilia anchoring structures, the basal bodies, or of ciliary function. "In summary, the rmnd5a morphant phenotype resembles several alterations known in ciliopathies, with particular overlap in the more severe spectrum of ciliopathies." (PMID 35543155, 2022). "To test whether rmnd5a morphants develop ciliopathy and/or SHH loss-of-function-related phenotypes, we suppressed the function of Rmnd5a using antisense oligonucleotides (morpholino, rmnd5a-mo)." (PMID 35543155, 2022).
head and neck cancer (1 paper, 2020). A primary or metastatic malignant neoplasm affecting the head and neck. "Specifically, for head and neck cancer, the expression levels of three genes, NFE2L2, RMND5A and SLC44A1, were associated with increased smoking-related mutational signature, while an inverse association was observed for one gene, ARRB1." (PMID 32928150, 2020).
microphthalmia (1 paper, 2022). Congenital or developmental anomaly in which the eyeballs are abnormally small. "The microinjection of rmnd5a-mo into one blastomere at the two-cell stage resulted in developmental alterations, including brain anomalies reminiscent of occipital encephalocele and severe eye anomalies reminiscent of microphthalmia." (PMID 35543155, 2022).
occipital encephalocele (1 paper, 2022). "Interestingly, a patient with a giant occipital encephalocele and craniofacial anomalies carries a partial duplication of the RMND5A gene." (PMID 35543155, 2022).
pancreatic adenocarcinoma (1 paper, 2024). "Previous studies have demonstrated that RMND5A expression is significantly higher in the tumor tissues of pancreatic adenocarcinoma, stomach adenocarcinoma and thymoma compared to normal tissues, respectively." (PMID 38229133, 2024). "Also, RMND5A has been proven as a potential prognostic marker in breast cancer and pancreatic adenocarcinoma." (PMID 38229133, 2024). "In addition, RMND5A is reported to positively regulate the migration of HeLa and pancreatic adenocarcinoma cells." (PMID 38229133, 2024).
tumor (9 papers, 2017 to 2025). "In this study, we show that downregulation or knockout of CTLH complex subunits RanBPM and RMND5A (Required for Meiotic Nuclear Division 5A) lead to increased cell proliferation and that RanBPM downregulation promotes tumour formation in a mouse tumour model." (PMID 30795516, 2019). "Finally, depletion of CTLH subunits RMND5A (required for meiotic nuclear division 5A) and RanBPM resulted in enhanced proliferation and loss of RanBPM promoted tumour growth in a mouse model." (PMID 30795516, 2019). "Further investigation is needed to determine whether RMND5A mediates the effects of miR-21 on tumor metabolism in a subset of HCC patients." (PMID 29538313, 2018). "Also, RMND5A might be a putative tumor suppressor as a strong candidate target of miR-21 in human hepatocellular carcinoma." (PMID 31885576, 2019).
cancer (7 papers, 2014 to 2025). A tumor composed of atypical neoplastic, often pleomorphic cells that invade other tissues. "Required for meiotic nuclear division 5 homolog A (RMND5A), a novel ubiquitin E3 Ligase, has been reported to correlate with poor prognosis of several cancers." (PMID 38229133, 2024). "We find miR-138 target RMND5A is a common phenomenon in other cancer cells such as human airway cell line and TSCC cell line by gathering information from publicly available microarray data in GEO." (PMID 24057215, 2014). "In addition to being amplified, the RMND5A gene locus at 2p11.1 has been shown to be also deleted or in a variety of cancers." (PMID 31885576, 2019). "Previous studies demonstrated that miR-21 is consistently overexpressed in a variety of cancers including OSCC, and RMND5A is a strong candidate target of miR-21." (PMID 38229133, 2024). "Some of these reported targets are cancer-related and are associated with carcinogenesis (such as SPRY2, SKY and SRSF3), cancer prognosis (such as CNOT6, RECK and GID4) or cancer cell plasticity (such as RMND5A)." (PMID 33804639, 2021).
infection (3 papers, 2024 to 2026). The state of being infected such as from the introduction of a foreign agent such as serum, vaccine, antigenic substance or organism. "In this study, overexpression of RMND5A in human umbilical vein endothelial cells (HUVECs) was performed via lentiviral infection, followed by MTT, would healing and tube formation assay as well as signaling analysis." (PMID 38229133, 2024).
RMND5A also shares sentences with these, for which no sentence is quoted: developmental delay (2 papers); gastric cancer (2); Intellectual disability (2); myeloproliferative disease (2); neurodegenerative disease (2); ovarian carcinoma (2); Skraban-Deardorff syndrome (2); adenocarcinoma (1); Alzheimer disease (1); Atrophy (1); Huntington disease (1); Hypoglycemia (1); infectious disease (1); intellectual disability syndrome (1); laryngotracheitis (1); lung carcinoma (1); lymphoid tumors (1); lymphoma (1); Oral cancer (1); Seizure (1); squamous cell carcinoma (1); stomach adenocarcinoma (1); tauopathies (1); thymoma (1); viral infection (1).